TSPAN7 (tetraspanin 7)
Description:
May be involved in cell proliferation and cell motility.
Synonyms: TALLA-1; CD231; A15; DXS1692E; MXS1; TM4SF2; CCG-B7; MRX58; TM4SF2b; XLID58
Tractability: Antibody: its Gene Ontology location is reachable by antibodies, with high confidence; UniProt predicts a signal peptide or a membrane-spanning region. PROTAC: ubiquitination databases record sites on it; its protein half-life has been measured.
Gene: Protein-coding gene on chromosome X (38,561,498 to 38,689,249, forward strand). Ensembl gene ENSG00000156298.
Subcellular location: Membrane
Pathways (Reactome):
Hemostasis: Cell surface interactions at the vascular wall
Neuronal System: Trafficking of GluR2-containing AMPA receptors
Gene Ontology:
Molecular function: protein binding
Cellular component: plasma membrane; membrane
Gene-disease validity (ClinGen):
ClinGen rates the evidence that TSPAN7 causes each of these diseases.
non-syndromic X-linked intellectual disability (X-linked): Moderate. Nonspecific X-linked intellectual deficiencies (MRX) belong to the family of sex-linked intellectual deficiencies (XLMR).
Homologues: Orthologues: chimpanzee TSPAN7 (100% identical), dog TSPAN7 (99% identical), guinea pig TSPAN7 (99% identical), pig TSPAN7 (99% identical), macaque PRRG1 (99% identical), mouse Tspan7 (98% identical), rat Tspan7 (98% identical), rabbit TSPAN7 (90% identical), tropical clawed frog tspan7 (90% identical), zebrafish tspan7 (84% identical), rat LOC102551255 (65% identical). Paralogues in human: TSPAN6 (58% identical), CD151 (31% identical), CD63 (30% identical), TSPAN11 (27% identical), TSPAN33 (27% identical), TSPAN18 (26% identical), TSPAN17 (26% identical), TSPAN3 (26% identical), CD9 (25% identical), CD82 (25% identical), TSPAN1 (25% identical), TSPAN9 (24% identical), and 20 more.
Diseases named in the same sentence as TSPAN7 in open-access papers:
TSPAN7 is named in the same sentence as 73 diseases in open-access papers, as found by Europe PMC text mining. Sharing a sentence is not in itself a finding about the gene and the disease. The quoted sentences say what the papers report.
bladder cancer (8 papers, 2016 to 2024). "Conversely, in bladder cancer, overexpression of Tspan7 inhibits p-PI3K and p-AKT, thereby inhibiting the proliferation of bladder cancer." (PMID 38649381, 2024). "Although TSPAN7 is an anti-tumor factor in bladder cancer, it promoted lung cancer progression by inhibits the expression of E-cadherin and vimentin, which raises the level of N-cadherin." (PMID 36512456, 2023). "At present, many studies are exploring antitumor strategies based on PTEN, such as the inhibitory effect of TSPAN7 on bladder cancer." (PMID 35864529, 2022). "In addition, overexpression of tetraspanin 7 inhibits the growth of bladder cancer cells via the PTEN/PI3K/AKT pathway." (PMID 39031113, 2024). "Tetraspanin 7 is also thought to play a role in bladder cancer progression." (PMID 39031113, 2024). "Interestingly, tetraspanin 7 (TSPAN7) is currently known for its anticancer effect as it inhibits the PI3K/Akt‐dependent signaling pathway in bladder cancer." (PMID 39031113, 2024). "In contrast, Tspan7 suppresses proliferation in bladder cancer by inhibiting p-PI3K and p-AKT." (PMID 38649381, 2024). "However, the tumor-suppressing effect of TSPAN7 has been reported in myeloma and bladder cancer." (PMID 36941633, 2023). "Another interesting candidate is TSPAN7 that has an anti-tumor effect in some cancers such as bladder cancer but not in others such as lung cancer." (PMID 34207462, 2021). "Though further investigations are needed, these studies support the possibility of using TSPAN7, AKR1C1/2, and CYR61 as biomarkers for resistance and that knockdown or inhibition of these genes may prevent or reduce platinum chemoresistance in bladder cancer." (PMID 26799320, 2016). "The role of tetraspanin 7 (TSPAN7) has never been investigated in bladder cancer (BCa)." (PMID 33489923, 2020).
lung carcinoma (7 papers, 2020 to 2024). "Tspan7-mediated enhancement of EMT induction was recently reported to play a central role in lung cancer metastasis." (PMID 35524311, 2022). "There are reports in the literature that TSPAN 7 is upregulated in lung cancer cells, and its high expression is closely related to the poor prognosis of lung cancer patients, suggesting that TSPAN 7 plays an oncogenic role in lung cancer." (PMID 32694936, 2020). "We found through biochemical analysis that the expression of TSPAN7 was downregulated in gastric cancer, liver cancer and intestinal cancer, suggesting that TSPAN7 may play opposite roles in lung cancer and lung cancer." (PMID 32694936, 2020).
mental retardation (6 papers, 2008 to 2024). "Among them, the expression of TSPAN7 vary in different tissues, with the highest level in brain tissue, and multiple mutations in TSPAN7 have been implicated in intellectual disability." (PMID 36845098, 2023). "Mutation of the TM4SF2 gene (=Tspan7) is a cause of a severe intellectual disability and cognitive impairment." (PMID 35046772, 2021). "The ampakine CX516 has been shown to have positive effects on Tspan7 knockout mice, rescuing the intellectual disability phenotype, suggesting pharmacological modulation of AMPARs as a potential therapeutic target." (PMID 35046772, 2021). "Stable expression of Tspan7 is crucial for the structure of hippocampal neurons and normal synaptic transmission, and Tspan7 mutations are associated with intellectual disabilities, such as X-linked intellectual disability." (PMID 38389703, 2024).
X-linked intellectual disability (6 papers, 2017 to 2024). An X-linked intellectual deficiency in which not enough information is known, reported or published to indicate whether a gene causes non-syndromic or syndromic presentations. "In fact, Tspan7, homologous to Tspan6 and associated with X-linked intellectual disability, has been described to play a role in synapse development in vitro." (PMID 28207852, 2017). "The function of Tspan7 is not well understood; however, as TSPAN7 is highly expressed in the brain, some studies using genetically engineered mice have suggested that it is involved in X-linked intellectual disabilities." (PMID 39000307, 2024). "Finally, PICK1 also interacts with tetraspanin 7 (TSPAN7), in which mutations have been found in some types of X-linked intellectual disability." (PMID 30937469, 2019). "Interestingly, mutations in Tspan7, highly homologous to Tspan6, are associated with X-linked intellectual disability, suggesting that these two proteins are important for cognition." (PMID 28207852, 2017). "Mutations in Tspan7 have been associated with X-linked intellectual disability and impaired vesicle trafficking, cell surface receptor expression or dysregulated synapse development in the absence of functional Tspan7 may provide the molecular basis of the condition." (PMID 32314012, 2020).
clear cell renal cell carcinoma (5 papers, 2020 to 2023). "Consistent with our results, increased expression of TSPAN7, which can inhibit the development of multiple myeloma invivo, was associated with longer survival time in clear-cell renal cell carcinoma." (PMID 32084007, 2020). "Consistent with our results, higher expression of TSPAN7 is related to longer tumor-specific survival and disease-free survival in clear-cell renal cell carcinoma." (PMID 33033514, 2020). "In clear cell renal cell carcinoma, the higher the TSPAN7 gene expression, the smaller the number of TSPAN7-positive blood vessels, and the less infiltration and metastasis of the cells, suggesting that TSPAN7 may act as a tumor growth inhibitor and affect tumor progression and metastasis." (PMID 32694936, 2020).
multiple myeloma (4 papers, 2020 to 2023). "In multiple myeloma, TSPAN7 increases cell adhesion and is associated with improved survival." (PMID 33033514, 2020). "TSPAN7 significantly reduced tumor burden in 5TGM1/KaLwRij mice 4 weeks after intravenous injection of the murine myeloma cell line 5TGM1 by increasing cell adhesion to stromal cells and transendothelial migration, with no impact on cell proliferation." (PMID 36941633, 2023). "For example, the overexpression of Tspan7 in liver cancer and multiple myeloma cells markedly enhances their metastatic potential, whereas exerts an anti-tumor effects in bladder tumors and suppresses the growth of cancer cell through the PTEN/PI3K/Akt signaling pathway." (PMID 35524311, 2022).
ovarian carcinoma (4 papers, 2022 to 2025). A malignant neoplasm originating from the surface ovarian epithelium. "They identified two extracellular antigens, BDNF and TSPAN7, a secreted molecule associated with poor prognosis in ovarian carcinoma and a tetraspanin overexpressed in ovarian carcinoma, respectively." (PMID 37419983, 2023). "Only KTR14, KRT16, CXCL9, and CFD in BRCA1 Ovarian Cancer and TSPAN7 and CDKN2C in BRCA2 ovarian cancers were highly upregulated, and KANK4, MFGE8, LINC00346, and SA100A1 in BRCA1 mutated breast cancer, and MAGEA4 in BRCA2 breast cancers." (PMID 40647506, 2025). "As discussed in Part I, the authors identified IgA responses to BDNF and TSPAN7 autoantigens in ovarian cancer and found that recombinant BDNF and TSPAN7 IgA antibodies reduce xenograft tumor growth." (PMID 40356924, 2025). "For instance, in BRCA1-mut ovarian cancer, KTR14, KRT16, CXCL9, and CFD were highly upregulated (more than 4-fold change), and in BRCA2-mut ovarian cancers, TSPAN7 and CDKN2C were clearly upregulated (more than 2-fold change)." (PMID 40647506, 2025).
type 1 diabetes (4 papers, 2020 to 2024). "Better understanding of the structure of autoantibody epitopes will be important for optimising Tspan7 antibody assays for prediction and autoimmune categorisation of type 1 diabetes, and potentially of other organ-specific inflammatory diseases such as GPA." (PMID 32314012, 2020). "Antibodies to Tspan7 were detected in 26% of the Chinese type 1 diabetes patients, lower than the frequency of Tspan7 antibodies found in Caucasian patients with a similar assay." (PMID 32314012, 2020). "This review focuses on a member of the tetraspanin family, tetraspanin-7 (Tspan7) that has recently been discovered as a potentially important target of autoimmune responses in type 1 diabetes." (PMID 32314012, 2020). "Tetraspanin-7 (Tspan7) was confirmed as a target of autoantibodies in type 1 diabetes by the ability to immunoprecipitate both the natural and recombinant protein expressed by cell lines by autoantibodies in patients’ sera." (PMID 32314012, 2020). "Unlike radioligand binding assays with antigen transcribed in vitro, LIPS assays have proved capable of detecting of Tspan7 autoantibodies in type 1 diabetes." (PMID 32314012, 2020). "Establishing procedures to express or synthesise constructs that maintain the integrity of the autoantibody epitopes will be important for reliable detection of Tspan7 antibodies as markers of type 1 diabetes." (PMID 32314012, 2020). "It is now recognised that there are multiple targets of the autoimmune response in type 1 diabetes, the most recently identified being a member of the tetraspanin family, tetraspanin-7." (PMID 32314012, 2020). "This review describes the discovery of tetraspanin-7 as a target of autoantibodies in type 1 diabetes and how the detection of autoantibodies to the protein provides a valuable marker for future loss of pancreatic beta-cell function." (PMID 32314012, 2020). "Tspan7 is established as an autoantigen in type 1 diabetes and may be considered a potential target for antigen-specific immune intervention to prevent disease in individuals identified as being at risk." (PMID 32314012, 2020). "In addition, Tspan7 autoantibody can be used as a marker in type 1 diabetes and can distinguish individuals with latent autoimmune diabetes among adults characterized by the gradual decline in β-cell function, indicating its potential as a valuable target for immunotherapy in type 1 diabetes." (PMID 38389703, 2024). "The observation that autoimmunity in type 1 diabetes is directed to a relatively short regions of Tspan7 should assist in identifying T cell and B cell epitopes and will facilitate future studies to establish the importance of Tspan7 autoimmunity in the prediction and prevention of type 1 diabetes." (PMID 32314012, 2020).
autism (3 papers, 2008 to 2023). Persistent deficits in social interaction and communication and interaction as well as a markedly restricted repertoire of activity and interest as well as repetitive patterns of behavior. "TM4SF2 or tetraspanin 7 (TSPAN7) at Xp11.4 was found partially duplicated in two unrelated subjects with autism in our sample." (PMID 18925931, 2008).
colorectal cancer (3 papers, 2020 to 2025). A primary or metastatic malignant neoplasm that affects the colon or rectum. "Despite its recognized significance, the role of TSPAN7 in colorectal cancer (CRC) remains unexplored." (PMID 41031049, 2025). "Considering that the pathological types of gastric cancer and colorectal cancer are both adenocarcinoma, while liver cancer is cell carcinoma, the expression of TSPAN7 may be different depending on the tumor site and tissue pathology." (PMID 32694936, 2020). "However, there are no reports on the expression of TSPAN7 in liver cancer, colorectal cancer and gastric cancer." (PMID 32694936, 2020).
liver cancer (3 papers, 2020 to 2024). An epithelial or non-epithelial malignant neoplasm that arises from the liver. "Since the four-transmembrane protein family also directly or indirectly participates in the process of cell proliferation, invasion and metastasis, we hope to understand what role Tspan7 plays in liver cancer cells." (PMID 32694936, 2020). "We found that compared with normal cells, the expression of TSPAN7 in liver cancer cells was significantly reduced, while the expression of gastric and colon cancer was not significantly different from that of normal cells." (PMID 32694936, 2020). "We selected HCC-LM3 cells for LV-Tspan7 transfection to better understand the effect of Tspan7 on the proliferation of liver cancer cells." (PMID 32694936, 2020). "In subsequent studies, we mainly studied the role of Tspan7 in liver cancer cells." (PMID 32694936, 2020). "After summarizing the TSPAN family and its different correlations in various types of tumorigenesis, this study explored TSPAN7 in hepatoma cells in detail and concluded that TSPAN7 may be a potential biomarker for liver cancer." (PMID 32694936, 2020). "Through real-time PCR and Western blot experiments, we found that compared with normal cells, the expression of TSPAN7 in liver cancer cells was significantly reduced, while its expression in gastric and colon cancer was not significantly different from normal cells." (PMID 32694936, 2020). "We found some members of the TSPAN family show significant expression differences between cancer and normal tissues, of which TSPAN7 may be a potential biomarker for liver cancer." (PMID 32694936, 2020). "Therefore, we believe that TSPAN7 plays a tumor suppressive role in liver cancer cells." (PMID 32694936, 2020). "As shown by our study, the high expression of Tspan7 significantly inhibited the proliferation, invasion, and metastasis of HCC-LM3 human liver cancer cells." (PMID 32694936, 2020). "The results showed that the high expression of Tspan7 not only inhibited the proliferation of HCC-LM3 cells but also inhibited the invasion and metastasis of liver cancer cells." (PMID 32694936, 2020).
osteosarcoma (3 papers, 2022 to 2024). A usually aggressive malignant bone-forming mesenchymal neoplasm, predominantly affecting adolescents and young adults. "Most importantly, tetraspanin 7 promotes osteosarcoma cell invasion and metastasis by inducing EMT and activating the FAK‐Src‐Ras‐ERK1/2 signaling pathway." (PMID 39031113, 2024). "In these studies, inhibition of tetraspanin 7 expression led to a concomitant reduction in the migratory capacity of osteosarcoma cells." (PMID 39031113, 2024). "According to available data, tetraspanin 7 is highly expressed in tissues from patients and commercially available osteosarcoma cell lines." (PMID 39031113, 2024). "Previous studies have also investigated the role of tetraspanin 7 in the activation of the ERK signaling pathway in human osteosarcoma cells MG‐63, U2OS and HOS." (PMID 39031113, 2024). "TSPAN7 is highly expressed in primary osteosarcomas and promote osteosarcoma cell growth, EMT process, and in vivo metastasis." (PMID 36941633, 2023). "How Tspan7 influences the onset or progression of osteosarcoma (OS), however, remains to be defined." (PMID 35524311, 2022). "Additionally, increased expression of tetraspanin 7 has been detected in primary osteosarcoma tumors and osteosarcoma cell lines." (PMID 39031113, 2024).
acute lymphoblastic leukemia (2 papers, 2016 to 2024). Leukemia with an acute onset, characterized by the presence of lymphoblasts in the bone marrow and the peripheral blood. "Increased levels of TSPAN7 in patients with acute lymphoblastic leukemia, chronic myeloid leukemia, or acute myeloid leukemia are associated with drug resistance." (PMID 26799320, 2016).
Alzheimer disease (2 papers, 2023 to 2024). A progressive, neurodegenerative disease characterized by loss of function and death of nerve cells in several areas of the brain leading to loss of cognitive function such as memory and language. "The published datasets also showed that the expression of TSPAN7 was decreased in the brain tissues from patients of ASD, Huntington’s disease (HD), Parkinson’s disease (PD), and Alzheimer’s disease (AD) (*P < 0.05, **P < 0.01, n.s, not significant)." (PMID 36625203, 2023).
breast carcinoma (2 papers, 2023 to 2025). "Our study is the first to link CD74 and TSPAN7 expression with distant metastasis–free survival in breast cancer, highlighting gene signature based on CD74 and TSPAN7 as a predictor of metastasis development in BC, with a strong effect on patients’ distant metastasis–free survival." (PMID 36911401, 2023).
cognitive disorder (2 papers, 2020 to 2021). A disease affects cognitive processes. "Mutations in the TM4SF2 gene, which encodes TSPAN7, have been linked to human cognitive disorders." (PMID 32655390, 2020).
diabetes (2 papers, 2020 to 2024). "Follow up of these high-risk individuals indicated that the addition of Tspan7 antibodies as a predictive marker resulted in a small but insignificant increase in the probability of diabetes progression." (PMID 32314012, 2020). "With the identification of a fifth major target in Tspan7, the question then arises as to the importance of Tspan7 autoimmunity to diabetes prediction and prevention." (PMID 32314012, 2020). "It has been suggested that tetraspanin 7 may serve as an autoantigen in diabetes, making it useful for diabetes prediction and immunotherapy." (PMID 39031113, 2024). "Unfortunately, soon after the discovery of Tspan7 as an autoantibody target it was clear that radioligand binding assays with antigen transcribed and translated in vitro were not capable of detecting diabetes-associated Tspan7 antibodies effectively." (PMID 32314012, 2020). "Furthermore, the presence of Tspan7 antibodies predicted a faster decline in pancreatic beta-cell function in Chinese LADA patients, demonstrating that the novel autoantibody marker has value in predicting metabolic outcomes in specific diabetes patient groups." (PMID 32314012, 2020).